IL6 (interleukin 6)
Diseases named in the same sentence as IL6 in open-access papers (continued):
Sharing a sentence is not in itself a finding about the gene and the disease.
tumor (continued). "The male TME is more often enriched in immune-suppressive cells such as tumor-associated macrophages, Tregs and MDSCs which secrete anti-inflammatory cytokines, such as IL-6, and chemokines that lead to reduced T cell function." (PMID 40589738, 2025). "The decrease in IL‐6 levels indicated a downregulation of cancer‐associated characteristics and restrained tumour growth." (PMID 39161078, 2025). "These tumor cells and tumor-associated macrophages can release high levels of IL-6 to form a vicious cycle." (PMID 39802656, 2025). "In pulmonary neoplasia, hyperactivation of inflammatory mediator production by tumour-associated alveolar macrophages yields marked surges in IL-6– and IL-1–related factors both locally and systemically, correlating with adverse clinical trajectories." (PMID 40943351, 2025). "In esophageal squamous cell carcinoma, ALDH1-positive tumors are associated with aggressive tumor growth, increased IL-6, augmented EMT, and MDSC activation." (PMID 41368628, 2025). "STAT3 activation, mediated by IL-6, inhibits the activation of T lymphocytes, tumor-associated macrophages (TAMs), NK cells, and neutrophils." (PMID 41357220, 2025). "The synergy between ALKBH5 and IL-6 secreted by tumor-associated macrophages activates the JAK2/p-STAT3 pathway in cancer cells, promoting the progression of non-small cell lung cancer." (PMID 40585991, 2025). "Low oxygen levels mark this microenvironment, the presence of immunosuppressive cells like regulatory T cells and hepatic stellate cells, and the secretion of tumor-associated cytokines such as interleukin-6 (IL-6) and transforming growth factor-β (TGF-β)." (PMID 40308592, 2025). "In colitis-associated cancer, IL-6 signalling is predominantly activated in intestinal epithelium and tumour-associated immune cells." (PMID 41153383, 2025). "For example, the combination of dasatinib and quercetin significantly decreases the number of senescent CAFs and alters the release of proinflammatory cytokines, including IL-6, which is linked to tumor progression." (PMID 40765820, 2025). "Constitutional symptoms such as fever, malaise, and weight loss are also frequent, likely mediated by tumor-derived interleukin-6 and other pro-inflammatory cytokines." (PMID 40641912, 2025). "One such approach involves tocilizumab, a humanized monoclonal antibody (mAb) that blocks both soluble and membrane-bound IL-6 receptors, thereby inhibiting IL-6-driven signaling pathways implicated in tumor progression, particularly in TNBC." (PMID 40868199, 2025). "These immunosuppressive features were consistent with the ssGSEA findings, which showed enrichment of pathways associated with immunosuppressive and tumor-promoting processes, including IL-6/STAT3 signaling, TGF-β signaling, hypoxia, EMT, and angiogenesis." (PMID 40643554, 2025). "Unfavourable pathologic characteristics such as higher tumour stage, positive lymph nodes and positive surgical margins were also associated with higher IL‐6 serum levels (all p < 0.05)." (PMID 41380167, 2025). "Elevated gene expression of IL-6 and IL-23 was significantly associated with advanced tumor stage (P < 0.001), histological grade 3 (P < 0.001), and post-menopausal status (P = 0.023)." (PMID 40612845, 2025). "In PDAC, lactate secreted by tumor cells stimulates IL-6 production from cancer-associated fibroblasts." (PMID 41152975, 2025). "Secondly, elevated CCL2 levels recruit tumor-associated macrophages (TAMs), which secrete IL-6 and activate STAT3, further promoting immune modulation." (PMID 40087784, 2025). "The Tumor IMmune Estimation Resource database was used to analyze the association between IL-6 expression and immune cell infiltration." (PMID 39781345, 2025). "Inflammatory cytokines, such as interleukin-1 (IL-1), interleukin-6 (IL-6), and interleukin-8 (IL-8), have been implicated in tumour progression by influencing the CSC population." (PMID 41321388, 2025).
tumor (continued). "Our previous studies found that USP24 shapes the tumor microenvironment (TME) by promoting the secretion of interleukin-6 (IL-6) in tumor-associated macrophages (TAMs) and cancer cells." (PMID 40238877, 2025). "Several tumor-related parameters, including systemic inflammatory markers and interleukin-6 (IL-6), have been implicated in atherosclerotic progression." (PMID 40295953, 2025). "Platinum-based chemotherapy further alters histone dynamics in the TME by inducing IL-6 secretion from CAFs, which drives stemness-associated pathways in residual tumor cells." (PMID 41301911, 2025). "IL‐6, secreted by primary tumor cells and associated stromal cells, promotes PMN formation by activating STAT3 in tumor cells and tumor‐infiltrating myeloid cells." (PMID 40470380, 2025). "The STAT3-stimulating activity of IL-6 has recently been associated with the suppression of T cell anti-tumor activities." (PMID 39652104, 2025). "For example, Tumor-Associated Macrophages (TAMs) can secrete IL-6, which induces EMT in primary tumor cells through JAK2/STAT3 signaling, yielding anoikis-resistant CTCs." (PMID 41239272, 2025). "Our study group has previously linked high IL‐6 expression to aggressive tumour behaviour and poor prognosis." (PMID 41380167, 2025). "Its oncogenic effect has been linked to IL-6-induced transcription of intermediary molecular factors that drive cell cycle progression, angiogenesis, tumor invasiveness and metastasis." (PMID 41019062, 2025). "Persistent inflammation supports tumor growth, metastasis, and therapy resistance, with IL-6 in particular implicated in drug resistance within the TME." (PMID 41071399, 2025). "These present findings underline the importance of IL-6-caused trans activation as an important part of HNSCC tumor biology." (PMID 38672565, 2024). "These causes include 1) Direct tumor influence: Tumor cells produce cytokines like IL-1, IL-2, IL-6, and TNF-α, promoting tumor growth, disrupting normal cellular metabolism, and compromising bodily functions." (PMID 39872045, 2024). "PHF8 has also been implicated in tumor immune responses and its association with interleukin-6 (IL-6) has been validated in a number of cancer types." (PMID 39311138, 2024). "In a number of in vitro and cell line experiments, targeted inhibition of IL6-Rα abrogated these effects, consistent with a model in which IL-6 is a driver of tumorigenesis in tumor types often associated with PC." (PMID 38689325, 2024). "Tumor-associated microglia, in particular, can protect cancer cells from radiation-induced apoptosis by secreting cytokines like IL-6 and TNF-β, as well as increasing chemotherapy tolerance by upregulating drug efflux pumps." (PMID 38523646, 2024). "A recent study has highlighted the role of TAM-derived IL-6, particularly in EGFR mutant NSCLC, revealing that IL-6 can augment the immunotherapy resistance of tumor cells with EMT-associated resistance to EGFR-TKI." (PMID 39286635, 2024). "Acting as proinflammatory factor.Activating endothelial cells which will enhance the permeability of microvascular.Causing the necrosis of tumor cells.Promoting the secretion of other proinflammatory factors like IL‐1, IL‐6, IL‐12." (PMID 37985923, 2024). "IL-6 levels are directly associated with tumor stage, weight loss, and survival in lung and gastrointestinal cancer patients, as evidenced by studies." (PMID 38802952, 2024). "IL-6 is associated with MDSC accumulation and targeting IL-6 is one strategy to reduce MDSC suppression of anti-tumor immunity." (PMID 39188677, 2024). "Surprisingly, our findings recognized that the IL-6 variant is meaningfully affected on the tumor size in NSCLC patients." (PMID 38103126, 2024). "In contrast, gastric iCAFs were associated with dismal prognosis due to the upregulation of tumor-driving cytokine IL-6 and CXCL1/2 chemokines." (PMID 38562556, 2024).
tumor (continued). "Cancer cells‐stimulated cancer‐associated fibroblasts (CAFs) secrete higher amounts of IL‐6 and GM‐CSF that induce circulating monocytes recruited into the tumor microenvironment to differentiate into immunosuppressive TAMs." (PMID 38703051, 2024). "Research has indicated that the activation of inducible nitric oxide synthase (iNOS) and interleukin-6 (IL-6) has the potential to elevate the risk of genetic modification and contribute to the advancement of chemoresistance and tumor progression." (PMID 39124760, 2024). "IL-6 played pivotal roles in the inflammation, causing the chronic inflammation, which promotes the progression of tumor." (PMID 38654350, 2024). "IL-6 can activate signaling pathways that lead to tumor proliferation, such as JAK-STAT3, associated with tumor cell proliferation and resistance to chemotherapy." (PMID 38509620, 2024). "Elevated levels of IL-6 are associated with various types of cancers, contributing to the proliferation, survival, and migration of tumor cells." (PMID 38711918, 2024). "These released growth factors promote the proliferation of cancer cells in the bone, further fuelling tumour growth which, in turn, produce more PTHrP, IL-1B and IL-6 to consequently cause a positive feedback loop." (PMID 38800348, 2024). "• Transfection of downregulated miRNA mimics into CRC cell lines resulted in downregulation of TLRs that was associated with reduction in IL6 protein and tumor growth." (PMID 38987740, 2024). "In the tumour microenvironment, tumour-associated factors such as VEGF, TGFβ, IL-6, and PD-1 impair myeloid cell functions, resulting in inhibition of the anti-tumour immune response, which further promotes tumour growth." (PMID 38893071, 2024). "IL-6 is a promoter of G-CSF, is associated with tumor progression, and is thought to influence anti-tumor immunity through various mechanisms." (PMID 39739128, 2024). "Dysbiosis can stimulate the activation of tumor-associated macrophages (TAMs) and the accumulation of pro-inflammatory factors such as IL-6 and TNF-α, which promote OC progression by inducing EMT." (PMID 39497925, 2024). "In cases without apparent mutations, the activation of the pathway in tumor cells often stems from an increase in factors that induce activation of the pathway’s upstream receptors—such as cytokines like IL-6, TNFα, and IL-1—within the tumor microenvironment." (PMID 38331871, 2024). "ALKBH5 and tumor-associated macrophage-secreted IL-6 showed a synergistic effect to activate the JAK2/p-STAT3 pathway in cancer cells." (PMID 38872221, 2024). "The role of the YAP1-induced IL-6–associated signaling cascade in regulating the tumor microenvironment (TME) has been poorly understood, particularly in UCB." (PMID 39630608, 2024). "In various tumor entities, an association of elevated IL-6 serum levels with weight loss as well as poor performance status was shown." (PMID 38539528, 2024). "In liver cancer, tumor cells promote the recruitment and expansion of MDSCs within the TIME by releasing hypoxia-inducible factor 1-alpha (HIF-1α) and tumor-associated cytokines, such as IL-6, IL-1β, GM-CSF, G-CSF, VEGF, MCP-1, and MIF." (PMID 39596288, 2024). "Patients facing higher rates of tumor-associated mortality also tend to exhibit higher levels of specific cytokines (e.g., IL-6, IL-17A, IL-22, and transforming growth factor-β (TGF-β))." (PMID 39267848, 2024). "Considering the limited sensitivity of individual detection, we assessed the diagnostic performance of IL-6 combined with the traditional tumor markers CEA and CYFRA21-1 in AIS patients." (PMID 38529301, 2024). "Kaplan Meier survival analysis indicated that high expression of IL6 within the tumour-associated stroma was predictive of reduced CSS in the full cohort (HR = 1.974, 95%CI; 1.009–3.860, p = 0.042)." (PMID 39766336, 2024).
tumor (continued). "In comparison, it is more plausible to target the upregulated FXR in NSCLC that specifically induces the excessive or pathogenic IL-6/Jak2/STAT3 signaling pathway on the matter of tumor metastasis." (PMID 38360812, 2024). "Regarding the association between IL-6 and clinical features, interestingly, IL-6 levels were found to be higher in subjects with poorly differentiated histology, higher tumor burden, lower albumin levels, and liver metastasis." (PMID 38672257, 2024). "Tumor-derived IL-6 has been shown to be significantly associated with tumor size, stage, and proliferative activity as measured by Ki-67; as a result, it will probably increase with the disease progresses." (PMID 39464714, 2024). "Concerning the association of IL-6 serum levels and tumor stage, one such study found a significant association of advanced staging of tumor and increasing IL-6 serum levels." (PMID 38978990, 2024). "Within the GBM TME, IL-6 is secreted by tumor cells, glioma-associated microglia/macrophages (GAMs), and tumor-associated endothelial cells, with its expression induced by treatments such as chemotherapy and radiotherapy." (PMID 38994360, 2024). "Specifically, Enterococcus can reside within macrophages and neutrophils, stimulating the secretion of cytokines such as IL-6 and IL-10, which are associated with tumor development and immunosuppression." (PMID 38893183, 2024). "M2d macrophages, known as tumor-associated macrophages (TAMs), upregulate IL-6, IL-10, TGF-β, VEGF, and PD-L1 expression while depleting arginine to suppress T cell anti-tumor functions." (PMID 39662177, 2024). "Under inflammatory stimuli such as transforming growth factor-β (TGF-β), IL-6, and interleukin-10 (IL-10), tumor-associated macrophages (TAMs) are more likely to transition from the anti-tumor M1 phenotype to the pro-tumor M2 phenotype." (PMID 39290325, 2024). "We found that β-amyrin, lupeol, and quercetin inhibited the expression of IL-1β and IL-6, a result that is consistent with the point of view that inhibition of interleukin production also causes the inhibition of tumor cell growth." (PMID 39062057, 2024). "In comparison to the low BMscore group, the high BMscore tumor samples exhibited enrichment of genes associated with the “KRAS_SIGNALING_DN” and “IL6_JAK_STAT3_SIGNALING” pathways." (PMID 38365923, 2024). "Continuous activation of STAT3 by IL-6 signaling is linked to aggressive tumor behavior and poor patient prognosis in CRC." (PMID 39408697, 2024). "For instance, IL-6 can induce tumor-associated macrophages supporting tumor development, but IL-6 has also been associated with upregulation of CD40 on these macrophages." (PMID 39065651, 2024). "There also seems to be a correlation between high IL-6 levels and poor clinical features like heavy weight loss, advanced tumor stage and the presence of metastases as well as poor responses to treatment and prognosis." (PMID 38254757, 2024). "In the tumor immune microenvironment, other cell types also secrete IL‐6, such as tumor‐associated macrophages and fibroblasts." (PMID 39235042, 2024). "Interleukin-6 and C-reactive protein exhibit better diagnostic utility compared to traditional tumor markers in identifying OC, particularly in patients with OSCC." (PMID 38673838, 2024). "Tumor necrosis factor-alpha (TNF-α) and interleukin (IL)-6 levels are elevated in the tumor tissues and sera and associated with poor survival, increased tumor burden, and disease progression in patients with CRC." (PMID 39272794, 2024). "The results showed that smoking, weak sleep scores, maturity and advanced tumor stage were significantly associated with higher serum IL-6 concentrations." (PMID 38396821, 2024). "Tumor-associated fibroblasts can release a variety of chemokines and cytokines, such as IL-6 and CXCL2, to promote the migration and aggregation of Tregs cells into the TME, thereby transforming TME into an immunosuppressor." (PMID 39600941, 2024).
tumor (continued). "Here, we used PBMC‐ and THP‐1‐derived macrophages in vitro and tumour‐bearing mice in vivo to investigate the function and underlying mechanism of calycosin‐mediated inhibition of IL‐6 production in macrophages as well as the possible involvement of ER‐α36." (PMID 37974543, 2024). "IL-6 is associated with the accumulation of tumor-infiltrating lymphocytes and plays a role in regulating the survival, activation, and function of neutrophils through the IL-6/STAT3/PD-L1 signaling pathway." (PMID 38602594, 2024). "In MM, ALB level is also thought to reflect the damage to the liver caused by interleukin-6 produced in the tumor microenvironment." (PMID 39640278, 2024). "Inflammatory cytokines such as IL6 (and IL8, IL1B) are implicated in GBM tumorigenicity and progression, and IL6 in particular leads to JAK-STAT pro-tumor signaling." (PMID 39585062, 2024). "Elevated IL-6 levels have been associated with tumor progression in various cancer types and with treatment response." (PMID 39273323, 2024). "Recent studies indicate heightened myeloid infiltration corresponding to higher tumor-associated IL-6 expression in glioblastoma patients." (PMID 39690423, 2024). "A strong association has been reported between increased levels of interleukin-6 (L-6) in the tumor microenvironment, a major cytokine, and cancer." (PMID 38957610, 2024). "ARS affects signaling pathways and transcription factors associated with tumor growth, including the inhibition of the IL-6-JAK-STAT pathway, reduction of NF-κB p65 transcriptional activity, activation of p38 MAPK, and suppression of the Wnt/β-catenin pathway." (PMID 39840041, 2024). "Increasing data suggest that IL-6 plays a crucial role in the modulation of the function and activity of tumour-associated immune cells." (PMID 38398148, 2024). "There is evidence in the literature that deregulated IL6 expression is associated with tumor progression through inhibition of cancer cell apoptosis, stimulation of angiogenesis, and drug resistance." (PMID 38727303, 2024). "As it is well known that IL-6 is critical in shaping tumor-associated inflammation and in promoting cell proliferation after being produced by EGFR-expressing macrophages, we decided to evaluate gene expression by qRT-PCR of this proinflammatory cytokine." (PMID 38613413, 2024). "Loss of NF1, TSC1, or TβRII induced tumor cell-autonomous inflammatory reprogramming through alterations in chromatin accessibility and elevated IL6-JAK signaling." (PMID 38997291, 2024). "Here the authors show that EGC-derived IL-6 promotes the expansion of tumorigenic SPP1+ tumor-associated macrophages, associated with worse disease outcome." (PMID 39030280, 2024). "Previous findings showed that irradiation of tumor-associated fat pads increased cytokine secretion, including IL-6." (PMID 39338222, 2024). "Not only our earlier research but also recent studies have pointed out that IL-6 levels in serum or tissue were associated with disease status, including proliferative tumor activity, angiogenesis, metastasis, and patient prognosis in colorectal cancer (CRC)." (PMID 38256960, 2024). "CAFs are considered capable of suppressing antitumour immune responses mediated by T cells, tumour-associated macrophages, and secreted molecules, including IL-6 and TGF-β in HNSCCs." (PMID 38926351, 2024). "The stimulation of both TLR (Toll-like receptor) ligands and A2 adenosine receptor agonists or IL-6 can induce the differentiation of M2d macrophages, commonly known as tumor-associated macrophages." (PMID 39170251, 2024). "Overall, IL-6 is associated with several beneficial effects of exercise, including improved glycemic control, fat loss, tumor suppression, and muscle mass maintenance." (PMID 39337980, 2024). "In this prospective cohort study, elevated pre-diagnosis levels of IL-6 were associated with an increased risk of all-cause mortality among BC patients after adjusting for lifestyle factors, including BMI and tumour characteristics." (PMID 39342063, 2024).